IL10 (interleukin 10)
Diseases named in the same sentence as IL10 in open-access papers (continued):
Sharing a sentence is not in itself a finding about the gene and the disease.
infection (continued). "Alternative cellular-based immune mechanisms may, therefore, be involved in promoting an effective response to the infection, as is suggested by our results, in which IL-10 and IFN-γ may be used as potential markers of immune system response against ASFV infection." (PMID 34203976, 2021). "In addition, the increased IL-12/23p40 and IL-10 responses may suggest that T cell activation and regulation were increased in macaques after infection." (PMID 33941094, 2021). "During CR-Kp infection in mice, M-MDSCs recruited to the lungs early during infection (i.e., within the first 24 h) promoted efficient bacterial clearance, protected the lung against tissue damage, and improved host survival through a mechanism involving IL-10 production." (PMID 33558323, 2021). "For IL37 rs2723186, an association with CMV disease (p = 0.0499), for IL10 rs1800872, with graft loss or death (p = 0.0207) and for IL10 rs3024496, with infections (p = 0.0258) was observed in all patients, however did not hold true after correction for multiple testing." (PMID 33861738, 2021). "In addition, the anti-inflammatory cytokine IL-10 was one of the biological mediators that presented the most correlations in networks under all investigated conditions, except for resistant dogs after infection diagnosis." (PMID 33617528, 2021). "On the other hand, the production of IL-10 and the activity of regulatory T cells may downregulate the inflammatory process, limiting tissue damage and perhaps the effectiveness of parasite control in some infections." (PMID 34869064, 2021). "The destructive effect of inflammatory cytokines on the epithelial barrier is one of the ways that facilitates microbial pathogen infection, and this effect might be related to the type of epithelial cells, the levels of cytokines and the presence of anti-inflammatory cytokines such as IL-10." (PMID 34674760, 2021). "An explanation for this association could be that the up-regulation of angiotensin-converting enzyme 2 receptor (ACE2R) after infection may lead to the production of cytokines such as IL-1, IL-10, and IL-6, and the regulation of B cell activation is triggered to respond." (PMID 34430148, 2021). "Some of the anti-inflammatory cytokines such as IL-10 have a negative feedback regulation to Th1 cells, NK cells, and macrophages to effectively reduce the damage caused by inflammation, and hinder the removal of pathogens during infection." (PMID 34960654, 2021). "The mRNA of IL-4 on the 24th day after infection, IL-8 on the 24th and 40th days, and IL-12p40 on the 40th day were significantly up-regulated; IL-6 mRNA was up-regulated during the test period, while IL-10 mRNA was significantly down-regulated on the 3rd and 31st days after infection." (PMID 34988138, 2021). "However, IL-10 expression was increased during infection supporting disease progression." (PMID 33680991, 2021). "Furthermore, IL-10 derived from MCs exerts beneficial and detrimental effects on the maintenance of tissue homeostasis and in several immune-related diseases including contact hypersensitivity, auto-immune diseases, and infections." (PMID 34067047, 2021). "However, later studies confirmed that IL-27Rα−/− mice developed normal Th1 response after infection, and IL-27 could induce IL-10 and SOCS3 to suppress Th1 cells, suggesting the bidirectional role of IL-27 in Th1 cells." (PMID 34299138, 2021). "The absence of cutaneous sensitization against HDM may be due to the tolerogenic environment of the “modified” T2 response, such as regulatory T cells [40, Personal communication], IL10, and alternatively activated macrophages induced during helminths, that disappears when the infection is cured." (PMID 34197505, 2021). "The rapid and essential provision of IL-10 by conventional CD4 T cells raised the possibility that Plasmodium-specific effector CD4 T cells may be rapidly programed to express IL-10 within days of an initial Plasmodium blood-stage infection." (PMID 33529242, 2021).
infection (continued). "Using a T. congolense infection mouse model, relevant for bovine trypanosomosis, we demonstrate that during the chronic stage of infection hepatocyte-derived IL-10, but not myeloid cell-derived IL-10, regulates the main infection-associated immunopathologies and ultimately mediates host survival." (PMID 32012211, 2020). "This elevated IL-10 production may be due to the resolution of inflammatory response at the site of infection; as both lesion progression and parasite load are already controlled by this point, its presence would be to decrease pro-inflammatory factors, such as IFN-γ." (PMID 32867857, 2020). "After stratifying by Plasmodium infection density, submicroscopic infection was associated with increased peripheral concentrations of IFN-α and decreased concentrations of IL-6, while microscopic infections were associated with elevated levels of TNF, IL-10 and IL-5." (PMID 32365058, 2020). "Furthermore, we also showed that cytokines such as IL-1β, IL-6, TNF-α, IL-8, and IL-10 may act as indicators of a lethal outcome at the endpoint of the infection process." (PMID 33553280, 2020). "Thus far, both naturally occurring CD4+ Foxp3+ Tregs as well as myeloid cells (Ly6C- patrolling monocytes and alternatively activated macrophages (M2)) were found to be sources of IL-10, that limit to some extent the development of immuno-pathogenicity (including liver injury) during infection." (PMID 32012211, 2020). "For example, an infection study on mice has shown that T-bet deficiency (T-bet-/- mice) lead to increased Mycobacterium tuberculosis susceptibility, indicating that T-bet has a central function in the regulation of cytokine production (IFN-γ and IL-10) and in controlling the infection." (PMID 32326041, 2020). "Following peroral infection with 109 viable C. jejuni strain 81-176 cells on d0 and d1, the pathogen could stably establish within the intestinal tract of secondary abiotic IL-10−/− mice from either cohort as indicated by median fecal loads of approximately 109 CFU per g." (PMID 33255723, 2020). "Therefore, IL-10 was necessary for proinflammatory suppression in the host during infection." (PMID 32190083, 2020). "Then, we sought to determine whether, under IL-10 deficiency conditions, fenofibrate was able to promote a similar reduction using the single infection model, since IL-10 KO did not survive the co-infection infection (data no shown)." (PMID 33072115, 2020). "We showed that MAP infection and proliferation led to a delay in moDC maturation, as shown by an increase of anti-inflammatory cytokine IL-10 and CD103—a tolerogenic marker—at the time of infection, which we speculated might be caused by MAP’s ability to inhibit phago-lysosome fusion." (PMID 32635236, 2020). "Interestingly, LmJ3OE infections displayed a significantly lower expression of IL-4 and IL-10." (PMID 33114674, 2020). "Likewise, Th2-type cytokines, e.g., IL-4 and IL-10, were assessed for their functional effects in periapical bone destruction in a genetic study, which revealed the suppressive role of IL-10, but not IL-4, on infection-induced periapical bone loss." (PMID 32116745, 2020). "Similarly, the induction of cytokines that improve tissue regeneration in the course of infection or dampen overshooting cytokine storms (e.g. IL10) might be considered." (PMID 33137201, 2020). "Thus, during the course of infection, viral IL-10 ensures a supply of monocytes, which may aid in HCMV dissemination." (PMID 32477336, 2020). "IL-10 could be produced by regulatory T cells as a result of infection-induced inflammation." (PMID 31952232, 2020). "The reversibly non-motile C. jejuni isolate (11168mot-) in this work was either cleared from the mouse GI tract before it could establish infection in the C57BL/6 IL-10–/– mouse model or colonized to significantly lower levels than wild-type (11168wt) and the revertant 11168mot+." (PMID 33240235, 2020).
infection (continued). "IL-22 belongs to the IL-10 cytokine family and is produced in the intestinal mucosa by group 3 innate lymphoid cells (ILC3s; produces IL-22 during the early stage of infection) and CD4 + T cells (including Th17 cells and Th22 cells; produces IL-22 during late stage of infection)." (PMID 32082288, 2020). "However, studies in macaques infected with recombinant viruses showed that the lack of RhCMV UL111A has profound effects in the magnitude of both innate and adaptive host immunity and indicate that RhCMV IL10 is important for dissemination of the virus during primary infection." (PMID 32582563, 2020). "However, the blockade of IL-10 signaling produced an increase in the CD11bhiLy6 Ghi neutrophil population, but the phenotypes of these neutrophils were different from those of the CD11bintLy6 Gint neutrophils from mice with controlled infections." (PMID 32403973, 2020). "However, it remains unclear if non-hematopoietic cells, such as hepatocytes, could also be a potential source of IL-10 during the course of the infection." (PMID 32012211, 2020). "Interestingly Liposomal-imipramine treatment was associated with decrease in IL-10 production irrespective of the nature of the input infection." (PMID 33240825, 2020). "Therefore, we investigated in more detail the role of hepatocyte-derived IL-10 in the outcome of experimental T. congolense infection, a model in which the systemic levels of IL-10 progressively increase during the course of infection in order to sustain host survival." (PMID 32012211, 2020). "In addition, the patients infected with TM have previously been reported to have higher TNF-α, IL-1β, IL-12, and IL-10 levels in vivo, and the infection of TM enabled the enhancement of the production of cytokines such as TNF-α, IL-1β, IL-6, and IL-12 by stimulating macrophages in vitro." (PMID 33488545, 2020). "Furthermore, clearance of infection-induced apoptotic cells by phagocytes suppresses autoimmune responses through the release of anti-inflammatory cytokines such as interleukin-10 (IL-10) and transforming growth factor-β (TGF-β), and the inhibition of pro-inflammatory cytokines." (PMID 32900001, 2020). "However, the actual mechanism whereby TFs stimulate DCs to secrete high levels of IL-10 and how this may possibly lead to viral persistence in the local environment and establishment of infection requires further investigation." (PMID 31978062, 2020). "Furthermore, IL-10 levels up to 8 ng/mL have been detected during infection with SUDV." (PMID 31547585, 2019). "Furthermore, by combining TNF-α responses with IL-10 and IL-1ra responses, patients could be accurately classified into one of these two infection states." (PMID 31024518, 2019). "The level of IL-10 was the highest in the immunized group; however, these levels were significantly lower in the immunized and infected group, suggesting that impact of recombinant protein alone was very strong, but this influence was balanced by the broad immune response to infection." (PMID 31681308, 2019). "The results obtained in this in vitro infection system reinforce the observation that inflammation characterizes AD and PD, suggesting that the ability of immune cells of these individuals to secrete IL-10 in response to a viral insult is defective or exhausted." (PMID 31455413, 2019). "Similar to other DC subsets, these cells were susceptible to infection with hRSV, and while they expressed increased amounts of CD80 and CD86 in response to this virus as compared to non-infected cells, they also expressed the inhibitory costimulatory receptor PD-L1 and secreted IL-10." (PMID 31057543, 2019). "Importantly, BT-11 targets the lanthionine synthetase C-like 2 (LANCL2) pathway, which happens to be central to inducing IL-10 production and amelioration of overt inflammation during infection, as shown in the context of influenza virus and H. pylori infections." (PMID 32039196, 2019).
infection (continued). "Consequently, it is not surprising that pathogens like E. cuniculi have evolved mechanisms to subvert macrophage function or that macrophages are a major source of IL-10 during infection, but in this case it is emphasized that the same occurred in the absence of the B-1 cell in XID group." (PMID 31536488, 2019). "However, we observed comparable viral loads and IFNγ response of T cells on day 16 post-infection between NKp46-Cre-Il10fl/fl mice and their control littermates, demonstrating that NK cell-derived IL-10 is dispensable in establishing immunosuppression in the salivary gland during MCMV infection." (PMID 31803193, 2019). "The action of IL10 appears to be solely responsible for the suppression of IL1B and IL6 production during G18 infection, thus supporting our hypothesis that IL10 induced during G18 infection is dampening down some of the transcriptional response of bMDM to infection." (PMID 31527895, 2019). "However, it was previously established that the IL-10 production during infection may correlate with the differing filovirus pathogenicity in a particular host species." (PMID 31547585, 2019). "Considering that CD163 and CD169 expression can be induced by IL-10 and IFN-γ respectively, and that IL-10 treatment increases PRRSV infectivity while IFN-γ decreases it, the role of these cytokine in the modulation of macrophage susceptibility to infection requires further investigation." (PMID 31442273, 2019). "However, the M. bovis strain specific differential effects of IL10 on the response of bMDM to infection may have profound effects on the course of in vivo infection and the progression of bovine TB." (PMID 31527895, 2019). "However, it is still unclear whether one type or multiple cell types actually provide that IL-10 rendering hosts less efficient in clearing the infection." (PMID 30881362, 2019). "We surmise that a small percentage of constitutive, MHC II+/IL-10- neutrophils may participate in disease resistance by aiding T cell activation, whereas MHC II+/IL-10+ neutrophils are induced early in infection and are limited in their capacity to activate T cells." (PMID 31889109, 2019). "Whilst a balance is required between excessive immunoregulation and excessive tissue damage in response to (intracellular) microbial infection, the critical point maybe the degree of relative (to proinflammatory mediators) upregulation of immunoregulatory cytokines (e.g., IL-10) post infection." (PMID 31100860, 2019). "High IL-10 expression levels by N. caninum-infected MØs were observed for both isolates (being higher for Nc-Spain1H) but not in MØs inoculated with HI tachyzoites, suggesting a modulatory role of live Neospora in the immune response generated during infection to guarantee host survival." (PMID 31114577, 2019). "To study the effect of NK cell-derived IL-10 in maintaining an immunosuppressive environment and viral persistence inside the salivary glands, we infected Il10fl/fl and NKp46-Cre-Il10fl/fl mice and analyzed the T cell response in salivary glands on day 16 post-infection." (PMID 31803193, 2019). "However, NOS2 mRNA levels were only affected by IL10 siRNA during G18 infection." (PMID 31527895, 2019). "Hence, IL-10 is produced by a specialized subset of “natural regulatory plasma cells” relevant during conditions of infection, but is also produced by a considerable proportion of mature bone marrow plasma cells that seem to modulate myeloid cells under steady state." (PMID 31214168, 2019). "Also, PGE2 (via IL-10 production) increases the phagocytic activity of Balb/c mice-derived B-1CDP cells (a particular B-1 cell type with phagocytic ability; Borrello and Phipps, 1999), but it impairs the ability of the mice to resist the infection." (PMID 30186271, 2018).
infection (continued). "We found lower IL-10 protein levels and a significant 10-fold decrease in IL-10 mRNA expression at 24 h post-infection in whole lung homogenates from wild-type mice treated with nemiralisib, indicating that PI3Kδ signaling can regulate IL-10 levels in the lung post infection." (PMID 30093657, 2018). "Thus, pattern recognition is essential for controlling mycobacterial growth by regulating optimum levels of the TNF/IL-10 ratio during the period of infection, while miR-21 levels could counterbalance or impair an adequate antimicrobial response." (PMID 29755459, 2018). "Infection of either IL-10-deficient mice or mice treated with IL-10 receptor blocking antibody resulted in increased numbers of either IFN-γ+ or IFN-γ+TNF+ CD8 T cells, suggesting that IL-10 suppresses CD8 T cell effector functions following respiratory virus infection." (PMID 29686673, 2018). "The decrease in serum IL-10 levels over the course of the infection was also delayed in LDA-treated mice, and although the AAS group showed the lowest values in late-stage disease, the anti-inflammatory effect observed, as represented by higher IL-10 levels at week 3, could be considered a problem." (PMID 29740435, 2018). "This was in keeping with our prior observations that nemiralisib treatment reduced IL-10 mRNA levels in the lung tissue of S. pneumoniae infected wild-type mice, suggesting a role for IL-10-producing CD19+B220- B cells in the PI3Kδ-dependent susceptibility to infection." (PMID 30093657, 2018). "Thus, the fact that all mice showed increased IL-10 levels but only BALB/c showed increased TGF-β levels at this infection time point may imply that these mice presented a more regulated and efficient response than those of C57BL/6 lineage." (PMID 29662478, 2018). "Furthermore, there was an increase of IL-10 expression in the serum at the late infection stage." (PMID 30037796, 2018). "Results showed that consistent with our in vitro blocking results, in vivo blocking with α-CD200 antibodies resulted in a significant reduction of IL-10 levels in LdWT infection (CD200R+ panel, p = 0.0065), suggesting that blocking CD200 signaling could alter the CD4+ T cell characteristics." (PMID 29915577, 2018). "To investigate vascular abnormalities in P. chabaudi-infected IL-10 KO mice, we examined sagittal sections of perfused and fixed brain tissue for evidence of vascular leakage as indicated by extravascular fibrinogen at the peak of infection (day 8 post-infection)." (PMID 29866139, 2018). "IL-10 production early in a rodent malaria infection has been found to prevent high parasite loads due to reduced Th1 responses and the absence of regulatory cytokines during the later stages of the infection resulted in the development of adverse immuno-pathology." (PMID 29970128, 2018). "Meanwhile, 1 mM NaO may exert pro-inflammatory effects prior to infection, with respect to IL-1β gene expression and secretion as well as chemokine gene expression, but it can act as an anti-inflammatory after infection due to the IL-10 and IL-1β gene expression and the IL-1β secretion." (PMID 28361042, 2017). "In EBOV-infected patients, fatal infection was associated with high levels of IL-10 and IL-1RA, modest levels of TNF-α and IL-6, and non-detectable levels of IL-1β, MIP-1α, and MIP-1β, while survivors were characterized by high levels of TNF-α, IL-1β, and IL-6 in plasma." (PMID 28861075, 2017). "The host immune responses to these infections are also described, including how S. epidermidis seems to trigger low levels of pro-inflammatory cytokines and high levels of interleukin-10, which may contribute to the sub-acute and persistent nature often associated with these infections." (PMID 28824556, 2017).